CD4 (CD4 molecule)
Diseases named in the same sentence as CD4 in open-access papers (continued):
Sharing a sentence is not in itself a finding about the gene and the disease.
tumor (continued). "CY1-4 is a small molecule IDO/TDO inhibitor, which can effectively inhibit IDO/TDO-mediated immune resistance, relieve immunosuppressive TME and TDLN, significantly reduce Tregs, increase CD4+ T cells and CD8+ T cells, and improve the anti-tumor effect." (PMID 39728172, 2024). "In the TME of the TC-1 tumor, the T cell compartment, consisting of CD8+ and CD4+ Tconvs and FOXP3+ Tregs, comprised only 11.1% of the CD45+ hematopoietic cell infiltrate, as identified by flow cytometry." (PMID 38349740, 2024). "This phenomenon was also confirmed by multicolor immunofluorescence staining of CD4 and CD8 antibodies in tumor tissues." (PMID 38280084, 2024). "Based on the “ESTIMATE” and deconvolution algorithms, our results similarly showed that AUNIP was significantly positively correlated with tumor purity scores, and negatively correlated with immune scores, B-cells, CD8+ T-cells and CD4+ T-cells." (PMID 39148731, 2024). "In the tumor, the percentage of CD25+ Tregs among CD4+ T cells was slightly but significantly decreased after CD25-targeted NIR-DPR." (PMID 38915782, 2024). "While anti-PD1 ICI is thought to activate CD8+ T cells to target the tumor through MHCI interactions, CD4+ T cells can kill MHCII+ cells though FAS/FASL interactions." (PMID 38265267, 2024). "Tregs suppress the proliferation of CD4+ and CD8+ T cells, reducing anti-tumor immune responses and are closely related to tumor prognosis." (PMID 39104717, 2024). "Single-cell RNA-sequencing analysis of patient tumor-infiltrating lymphocytes revealed that CXCR3 was expressed by CD8+ and CD4+ T cells, whilst CXCL9 and CXCL10 were predominantly expressed by macrophages following dual ICI treatment." (PMID 38533720, 2024). "T lymphocytes, comprising CD4+ and CD8+ T cells, play a pivotal role in generating and regulating tumor antigen-specific immune responses." (PMID 38312647, 2024). "In most samples (96%), the CD4+ T cell frequency exceeded that of CD8+ cells, with decreasing numbers from central to peripheral tumor areas, and to tumor-free, contralateral testes." (PMID 38649788, 2024). "Specifically, CD4 + T cells, CD8 + T cells, THP-1-derived macrophages, and HFL1 fibroblasts were co-cultured with UPP1-overexpressing tumor cells." (PMID 38331898, 2024). "Machine learning classifiers based on DCE-MRI have the potential to accurately predict CD3+, CD4+, and CD8+ tumor-infiltrating lymphocyte expression levels in patients with AGC." (PMID 38549936, 2024). "Antigen-activated CD4+ T cells secrete IL-2, IFN-γ, and TNF-α that activate CD8+ T cells, helping them kill tumor cells." (PMID 38724673, 2024). "CD8 T cells, assisted by CD4+ T cells, can trigger the STAT3-Granzyme B (GzmB) pathway to eliminate tumor cells." (PMID 38672681, 2024). "To achieve this, we correlated the expression of GAL‐3 in frozen tumor samples with the infiltration of FOXP3+, CD4+, and CD8+ lymphocytes as well as the expression of these markers in FPEE from tumor and tumor‐near stroma compartment." (PMID 37567864, 2024). "Herein, we identified 6 factors, including hepatic metastases, tumor size, AC of CD3+, CD4+, CD8+, and B cells, were correlated with the efficacy of anti-PD-1 inhibitors and PFS in training cohort." (PMID 38833153, 2024). "Instead of approaching tumor cells, CD8+ T cells within CN3 showed a significantly closer distance between the nearest CD8+ T cells and CD4+ T cells than the other CD8+ T cells." (PMID 38611111, 2024). "Higher levels of pks+ E. coli were associated with lower levels of the serum C-reactive protein, fewer densities of CD4+ cells and CD163+ cells in the tumor microenvironment, and a reduction in the number of organs affected by recurrent metastasis." (PMID 39272861, 2024). "Craft and Joshi’s team found that B cells presenting tumor antigens can promote the differentiation of tumor-specific helper CD4+ T cells, producing IL-21, enhancing anti-tumor CD8+ T cell responses, and thereby controlling tumor growth." (PMID 38696324, 2024).
tumor (continued). "As already discussed, CD4+ T lymphocytes and the TME influence each other, directly and indirectly, providing a complex and interdependent interaction in each type of tumor." (PMID 38690280, 2024). "This combination therapy increases the number and activation of CD4+ and CD8+ T cells, natural killer cells, and myeloid cells in both tumor and non-tumor tissues." (PMID 39290697, 2024). "cDC1 reprogramming synergized with anti-PD-1 or anti-CTLA-4 treatment leading to increased CR in B16 and B2905, which also resulted in expansion of tumor antigen-specific IFNγ+CD8+ and IFNγ+CD4+ T cells in peripheral blood." (PMID 39236156, 2024). "We noted an increase in the densities of CD4+T and CD8+ T cells in the tumor of the Pa + mAb group, while the density of FoxP3+ cells showed no significant change." (PMID 38961326, 2024). "CD4+ and CD8+ T cell distribution throughout the tumor area also indicated potent T cell infiltration in GL261 GBM models." (PMID 38298111, 2024). "High CRP levels often indicate an immunosuppressive tumor microenvironment, and CRP can induce the infiltration of M2 macrophages and regulatory T cells and inhibit the proliferation and function of CD4+ and CD8+T cells." (PMID 39555053, 2024). "This accumulation inhibits CD4+ and CD8+ T cells, primarily through the expression of myeloperoxidase (MPO) and Fas/FasL, thereby promoting tumor growth." (PMID 38474175, 2024). "The flow cytometry analysis of the blood and tumor of mice with induced tumor treated with combined treatment revealed elevated levels of CD83, CD86, CD8, and CD4 (76.3, 66.9, 83.7, and 14.4%, respectively)." (PMID 39062070, 2024). "CD4+ T cell density was significantly higher in the NTL and interface compartments than in the tumor (p = 0.004 and p = 0.003, respectively)." (PMID 38429349, 2024). "In CRC mouse models, these lymphocytes effectively eradicate the tumor, mainly comprising CD8+ T cells and CD4+ T cells." (PMID 39467702, 2024). "Following treatment with NK cells and RNK cells, there was a significant increase in the positive rates of macrophages, CD4+ T cells, and CD8+ T cells in both tumor tissues and spleens." (PMID 38891683, 2024). "Tumor cells express minOVA for the generation of OT-I and OT-II peptides for tracking CD8 + and CD4 + T cell responses, respectively, and additionally express ZsGreen for efficient recognition of tumor cells as well as phagocytes taking up tumor antigen." (PMID 38853999, 2024). "FOXP3+ Tregs, a subset of CD4 + T cells, are known for their immunosuppressive roles in the TME, often inhibiting the activity of effector T cells and promoting tumor growth." (PMID 38331898, 2024). "The number of CD4 + or CD8 + cells negatively correlates with biochemical recurrence and tumour-specific survival." (PMID 38825615, 2024). "Our results revealed that mice implanted with PRPS2 knockdown cells displayed an increased percentage of CD4+ and CD8+ T cells, accompanied by a decreased percentage of TAM, M‐MDSC, and PMN‐MDSC within the tumor tissues." (PMID 38952044, 2024). "For example, Th1 CD4+ cells secrete pro-inflammatory mediators INF-γ and TNF-α, and trigger the anti-tumor activity of NKs, thus activating a powerful anti-cancer immune response." (PMID 39050852, 2024). "Cancer immunotherapy utilizes the host immune system, especially CD4+ and CD8+ T cells, to attack tumor cells with different approaches like immune checkpoint inhibitors (ICIs), immunomodulators, and cancer vaccines." (PMID 38357542, 2024). "They then present these tumor-specific antigens through MHC class I and II molecules, activating CD8+T and CD4+T cells." (PMID 38384806, 2024). "FACS analysis showed that VVL-GL21 increased the number of CD4+ and CD8+ T cells within the tumor after treatment." (PMID 39830516, 2024).
tumor (continued). "Another interesting gene that is upregulated in Tregs with LOY is TIGIT, an immunosuppressive receptor found on tumour-infiltrating NK cells, CD8+, CD4 + and regulatory T cells, with highest abundance in the latter." (PMID 38443832, 2024). "Research shows that suppressive CD4+ Foxp3+ GATA3+ Treg cells proliferate in response to ST2/IL-33 signaling, both in vivo and in vitro, which aids in immunosuppression and tumor immune evasion." (PMID 40236667, 2024). "TILs are lymphocytes that enter tumor tissues, and they include multiple subtypes, such as CD8+ cytotoxic T cells, CD4+ helper T cells, regulatory T cells (Tregs), and B cells." (PMID 39697553, 2024). "We discovered that SCD in CD4+ T cells promote Th1 cell polarization and activation of the cytotoxic effect in CD8+ T cells within the tumor immune microenvironment." (PMID 39543650, 2024). "Here, we first detected the recovery of CD4+ Treg cells in circulation after surgical resection on CCA and HCC patients, suggesting restoration of immune system balance following tumor resection." (PMID 39408071, 2024). "The depletion of CD5 in DCs affected the expression of CD5 on CD4+ and CD8+ T cells, which affected tumor elimination in response to ICB therapy." (PMID 38261139, 2024). "The study has shown that interferon-γ (IFN-γ) induces tumor cells to express MHCII through MHC class II transactivator (CIITA), which is recognized and killed by cytotoxic CD4 + T lymphocyte (CD4 + CTL)." (PMID 38816871, 2024). "In vivo, the combination of Chrysin@mPDA and PTT significantly reduced tumor volume and weight, decreased estrogen receptor-positive cells, and increased infiltration of CD3+CD4+ and CD3+CD8+ T cells in tumor tissues." (PMID 39045563, 2024). "Immunofluorescence tumor sections from the saline group and blank LNP showed minimal infiltration of CD4+ and CD8+ T cells, indicating an immunosuppressive tumor microenvironment." (PMID 38675231, 2024). "In this study, high TIBs infiltration correlated with more CD4+T (p < 0.001) and CD8+T cells (p < 0.001) in RCC tumor sites." (PMID 38762825, 2024). "RCC tumour microenvironment (TME) is infiltrated by CD8+ T, CD4+ T, Natural Killer (NK) cells, macrophages, neutrophils, T regulatory cells (Tregs), and myeloid-derived suppressor cells (MDSCs)." (PMID 38704478, 2024). "In a syngeneic orthotopic mouse model of oral squamous cell carcinoma, tumors in Calca knockout mice were smaller than in wild type mice, and had an increased anti-tumor immune response, including CD8+ T cells and CD4+ T cells." (PMID 39050547, 2024). "An increase in the number of both CD4+ and CD8+ subtypes of TILs (tumor-infiltrating lymphocytes) after FUS treatment was also described." (PMID 39766134, 2024). "Many CD3+, CD4+, or CD8+ T cells were detected in the tumor microenvironment of TCR135-T cell–treated mice, while only a few scattered positive signals were seen in the TCRneg-T group." (PMID 38412034, 2024). "CD4+ and CD8+ T-cells were increased both around the periphery of the tumor but also at greater depth into the tumor than in the NS treated samples." (PMID 38204925, 2024). "Levels of CD4+ and CD8+ tumor-infiltrating T cells often correlate with improved clinical outcomes in various cancers." (PMID 39458338, 2024). "We observed a significant correlation between HOTAIR expression and tumor immune cell infiltration, including B cells, CD8+ T cells, CD4+ T cells, macrophages, neutrophils, and dendritic cells." (PMID 38696320, 2024). "The observed reduction in the percentage of CD4+ FoxP3 + regulatory T cells, while sparing CD8+ T cells, can lead to de-suppression of anti-tumor immune response and reduce tumor growth." (PMID 38503797, 2024).
tumor (continued). "The presence of CD4+CD25+TNFR2+T-regs in certain TMEs now appears to be clinically significant and demonstrates potent immunosuppressive functions, facilitating tumor escape from the immune response." (PMID 39609700, 2024). "A similar increase in CD4+ and CD8+ T cells post-treatment with an oncolytic AdV named Delta-24-RGD (DNX-2401) within glioma tumours of immune-competent Syrian hamsters was observed." (PMID 38732225, 2024). "Although CD4 T cells and MHC-II NeoAgs are critical components of anti-tumor immunity, we specifically chose to utilize an SLP vaccine against a single MHC-I NeoAg to definitively link the MHC-I NeoAg vaccine response to a specific defined NeoAg." (PMID 38187708, 2024). "They used DR4×Rag–/– mice inoculated with HLA-DR4–negative tumor cells in which the CD8 epitope was only present on the tumor cells and the CD4 epitope was only present on the host cells." (PMID 38412034, 2024). "TNF has also been reported to upregulate IL‐17A production by CD4+ T cells, thereby recruiting myeloid cells into the TME and enhancing tumor growth." (PMID 38566518, 2024). "Statistically significant differences were seen between zinc and CD19+CD69+ tumor, CD4+CD25+ node T lymphocytes and Cu and: CD3+CD69+, CD4+PD-1, CD8+PD-1 tumor, and CD4+PD-1, CD8+PD-1 node T lymphocytes." (PMID 38256645, 2024). "Based on the expression of the corresponding lineage markers in each group, we identified the major tumor-infiltrating immune cell populations comprising B cells, macrophages, CD8+ T cells, CD4+ T cells, NK cells, neutrophils, and dendritic cells." (PMID 39002018, 2024). "Both the 3D and X–Y optical sections results indicate segregation between the intratumor microbiome and the CD4+ and/or CD8+ compartments, suggesting activated T‐cells are excluded in bacteria‐colonized regions within the entire tumor tissue." (PMID 39378003, 2024). "The tumour is infiltrated by cytotoxic CD8+ T cells to kill tumour cells, a response that is often mediated by CD4+ T cells, which are trained for the immune response in the thymus." (PMID 38794272, 2024). "Using the stained samples, Crown Bio (UK) applied an image algorithm to detect CD4+ and CD8+ T-cells within 25 uM virtual segments around the tumor." (PMID 38204925, 2024). "We developed a novel immunohistochemical panel to assess prognostic outcomes and treatment sensitivity by detecting the expression of VCAN, CD3G, C1QB, CD68, CD4, and CD8 in both the TME and tumor cells of 190 DLBCL patients." (PMID 38980810, 2024). "Analysis of both biopsy groups revealed the presence of CD4+ and CD8+ T-cells within the tumor stroma." (PMID 39050748, 2024). "In animal models, DCsLEX-8086 not only inhibited tumor growth but also increased levels of CD4+ and CD8+T cells, along with M1 macrophages in the tumor microenvironment, while reducing Tregs." (PMID 39572459, 2024). "High-throughput genetic screening to identify targets in macrophages, dendritic cells, CD4+ T cells, and Treg cells within the TME can indirectly enhance the tumor-killing efficacy of adoptive T cell therapy." (PMID 39538305, 2024). "Their results showed that IBI323 significantly inhibited MC38 tumor growth through both CD8+ and CD4+ T cells and led to an increased number of cytokines producing cancer-specific T cells in the tumors and blood." (PMID 39796650, 2024). "Nevertheless, the anti-tumor effects of LCMV-specific memory CD8+ and/or CD4+ T cell transfer were abolished upon PBS or NDV-WT treatment." (PMID 38609488, 2024). "First, the number of lymphocytes and mature T cells in the TME, as well as the ratio of tumor-infiltrating CD8+ and CD4+ T cells, were all significantly increased compared with cisplatin treatment alone." (PMID 39343834, 2024). "We next evaluated the immune response at the tumor nodes and found that the RBC‐PEI‐AD11 group had abundant infiltration of CD8+ and CD4+ T cells at the tumor nodes, while the remaining three groups had only a small amount of T cell infiltration." (PMID 37997186, 2024).
tumor (continued). "We recently showed that an optimized AAV vaccine generated effective CD4+ and CD8+ T cell-driven anti-tumor immune responses at a dose of 1 × 1010 vg/mouse." (PMID 39559560, 2024). "Both conventional CD4+ T helper and CD8+ T cells are needed for an efficient anti-tumor immune response, while relative Treg enrichment generally correlates with poorer patient outcomes." (PMID 38384469, 2024). "To determine the relationship between CAFs and CD4+ TILs, we fluorescently stained CD4 and fibroblast-activation protein (FAP), a marker for CAFs in tumor tissue from 4T1 mouse model." (PMID 39543650, 2024). "As shown, depletion of either CD8+ or CD4+ T cells similarly abolished the therapeutic effects of NDV-GP and led to a significant reduction in long-term survival of MC38 tumor-bearing mice with LCMV memory." (PMID 38609488, 2024). "The combination of splenic UTMC with systemic aPD-L1 inhibited tumor growth and enhanced the frequency of splenic IFN-γ+ CTLs and IFN-γ+ CD4+ cells while reducing TGF-β+ CD11b+ cells." (PMID 38543305, 2024). "To further substantiate the roles of CD8 + T cells in TCR clonality, we analyzed the relationship between T cell infiltration and TCR clonality using IHC staining for CD3 (T cells), CD4 (helper T cells), and CD8 (cytotoxic T cells) in PSCC tumor samples." (PMID 38280010, 2024). "Classic lymphocyte subsets, including CD3+, CD4+, CD8+, B cells, and natural killer cells, play crucial roles in regulating immunity and specifically targeting tumor cells for destruction." (PMID 39483483, 2024). "The results of this study showed that high-dose AA increased the intratumoral infiltration of CD4+ and CD8+ T cells and macrophages into the tumor microenvironment, with increased production of granzyme B and interleukin-12." (PMID 39896806, 2024). "We collected tumor tissues from B6 albino males 7 days post-implantation, and stained for CD8, FoxP3, and CD4." (PMID 39591176, 2024). "Bmal1 depletion in mice promotes an anti-inflammatory state, disrupts CD4+ and CD8+ T cell distribution in lymph nodes, and increases tumour growth by reducing CD8+ T cells in tumours." (PMID 39566400, 2024). "On the other hand, only the CD4 + central memory T cells seemed to be more enriched in d-HGP (p-value = 0.073, adjusted for tumor cellularity)." (PMID 38548918, 2024). "Tumor-derived exosomes activate the cGAS-STING pathway in naive lymphocytes, activating Foxp3, STAT5, and SMAD3 to promote the transformation of naive CD4+ T cells into Treg cells, thereby mediating immunosuppression." (PMID 39464890, 2024). "Emerging evidences indicate that responses to immunotherapy rely on tumor infiltration by CD8+ T cells, CD4+ T cells, DC cells that are able to recognize and eradicate tumor cells." (PMID 38267865, 2024). "Although the number of T-cell populations did not significantly change among the treatment groups, BSV decreased the population of CD4-positive cells, whereas the number of CD8-positive cells increased in the tumor compared to CV-treated tumors." (PMID 38886756, 2024). "Lymphocytes, including effector T cells (CD4+ helper and CD8+ cytotoxic) and B cells, secrete EVs that influence tumor progression and the tumor microenvironment." (PMID 39062046, 2024). "When coated with epitopes, BPs elicited DC-mediated MHC I and MHC II antigen presentation, CD4+ and CD8+ T cell priming resulting in differentiation into CTLs capable of mediating effective anti-tumour immunity." (PMID 38263169, 2024). "The tumor tissue of 182 patients was stained by double immunohistochemistry for FOXP3, CD4, and CD8, and the number of different phenotypes was analyzed microscopically." (PMID 39200145, 2024). "HLA-A/B/C and B2M-staining scores correlated with CD4+, CD8+, and FOXP3+/CD4+ infiltrate ratios in various tumor subtypes; however, considerable heterogeneity was observed even amongst tumors of the same histologic subtype." (PMID 38473354, 2024).